PER1 (period circadian regulator 1)
Description:
Transcriptional repressor which forms a core component of the circadian clock. The circadian clock, an internal time-keeping system, regulates various physiological processes through the generation of approximately 24 hour circadian rhythms in gene expression, which are translated into rhythms in metabolism and behavior. It is derived from the Latin roots 'circa' (about) and 'diem' (day) and acts as an important regulator of a wide array of physiological functions including metabolism, sleep, body temperature, blood pressure, endocrine, immune, cardiovascular, and renal function. Consists of two major components: the central clock, residing in the suprachiasmatic nucleus (SCN) of the brain, and the peripheral clocks that are present in nearly every tissue and organ system. Both the central and peripheral clocks can be reset by environmental cues, also known as Zeitgebers (German for 'timegivers'). The predominant Zeitgeber for the central clock is light, which is sensed by retina and signals directly to the SCN. The central clock entrains the peripheral clocks through neuronal and hormonal signals, body temperature and feeding-related cues, aligning all clocks with the external light/dark cycle. Circadian rhythms allow an organism to achieve temporal homeostasis with its environment at the molecular level by regulating gene expression to create a peak of protein expression once every 24 hours to control when a particular physiological process is most active with respect to the solar day. Transcription and translation of core clock components (CLOCK, NPAS2, BMAL1, BMAL2, PER1, PER2, PER3, CRY1 and CRY2) plays a critical role in rhythm generation, whereas delays imposed by post-translational modifications (PTMs) are important for determining the period (tau) of the rhythms (tau refers to the period of a rhythm and is the length, in time, of one complete cycle). A diurnal rhythm is synchronized with the day/night cycle, while the ultradian and infradian rhythms have a period shorter and longer than 24 hours, respectively. Disruptions in the circadian rhythms contribute to the pathology of cardiovascular diseases, cancer, metabolic syndromes and aging. A transcription/translation feedback loop (TTFL) forms the core of the molecular circadian clock mechanism. Transcription factors, CLOCK or NPAS2 and BMAL1 or BMAL2, form the positive limb of the feedback loop, act in the form of a heterodimer and activate the transcription of core clock genes and clock-controlled genes (involved in key metabolic processes), harboring E-box elements (5'-CACGTG-3') within their promoters. The core clock genes: PER1/2/3 and CRY1/2 which are transcriptional repressors form the negative limb of the feedback loop and interact with the CLOCK|NPAS2-BMAL1|BMAL2 heterodimer inhibiting its activity and thereby negatively regulating their own expression. This heterodimer also activates nuclear receptors NR1D1/2 and RORA/B/G, which form a second feedback loop and which activate and repress BMAL1 transcription, respectively. Regulates circadian target genes expression at post-transcriptional levels, but may not be required for the repression at transcriptional level. Controls PER2 protein decay. Represses CRY2 preventing its repression on CLOCK/BMAL1 target genes such as FXYD5 and SCNN1A in kidney and PPARA in liver. Besides its involvement in the maintenance of the circadian clock, has an important function in the regulation of several processes. Participates in the repression of glucocorticoid receptor NR3C1/GR-induced transcriptional activity by reducing the association of NR3C1/GR to glucocorticoid response elements (GREs) by BMAL1:CLOCK. Plays a role in the modulation of the neuroinflammatory state via the regulation of inflammatory mediators release, such as CCL2 and IL6. In spinal astrocytes, negatively regulates the MAPK14/p38 and MAPK8/JNK MAPK cascades as well as the subsequent activation of NFkappaB. Coordinately regulates the expression of multiple genes that are involved in the regulation of renal sodium reabsorption. Can act as gene expression activator in a gene and tissue specific manner, in kidney enhances WNK1 and SLC12A3 expression in collaboration with CLOCK. Modulates hair follicle cycling. Represses the CLOCK-BMAL1 induced transcription of BHLHE40/DEC1.
Synonyms: PER; RIGUI; hPER
Tractability: PROTAC: UniProt records ubiquitination sites on it; ubiquitination databases record sites on it.
Gene: Protein-coding gene on chromosome 17 (8,140,467 to 8,156,506, reverse strand). Ensembl gene ENSG00000179094.
Subcellular location: Nucleus; Cytoplasm
Subcellular location (Human Protein Atlas): Cytosol; Nucleoplasm
Pathways (Reactome):
Circadian clock: Degradation of CRY and PER proteins; Phosphorylated BMAL1:CLOCK (ARNTL:CLOCK) activates expression of core clock genes; Phosphorylation and nuclear translocation of the CRY:PER:kinase complex; Phosphorylation of CLOCK, acetylation of BMAL1 (ARNTL) at target gene promoters; The CRY:PER:kinase complex represses transactivation by the BMAL:CLOCK (ARNTL:CLOCK) complex
Gene Ontology:
Molecular function: E-box binding; kinase binding; protein binding; RNA polymerase II cis-regulatory region sequence-specific DNA binding; ubiquitin protein ligase binding; chromatin DNA binding; transcription cis-regulatory region binding; transcription corepressor binding; DNA-binding transcription factor binding
Biological process: circadian regulation of gene expression; circadian rhythm; regulation of hair cycle; chromatin remodeling; entrainment of circadian clock; entrainment of circadian clock by photoperiod; negative regulation of canonical NF-kappaB signal transduction; negative regulation of DNA-templated transcription; negative regulation of JNK cascade; negative regulation of nuclear receptor-mediated glucocorticoid signaling pathway; negative regulation of transcription by RNA polymerase II; positive regulation of transcription by RNA polymerase II; post-transcriptional regulation of gene expression; regulation of circadian rhythm; regulation of cytokine production involved in inflammatory response; regulation of p38MAPK cascade; regulation of sodium ion transport; response to cAMP
Cellular component: cytoplasm; cytosol; nucleoplasm; nucleus
Genetic constraint (gnomAD): Loss-of-function variants: 87 observed, 123.95 expected, observed/expected ratio (o/e) 0.7, 90% interval 0.59 to 0.84. The upper end of that interval is the gene's LOEUF score, 0.84, which puts it in group 3 of 6, group 1 being the genes least tolerant of losing a copy. Missense variants: 1,761 observed, 1,674 expected, observed/expected ratio (o/e) 1.05, 90% interval 1.01 to 1.09. Synonymous variants: 797 observed, 702.68 expected, observed/expected ratio (o/e) 1.13, 90% interval 1.07 to 1.2.
Cancer hallmarks: escaping programmed cell death (promotes); escaping programmed cell death (suppresses); suppression of growth (promotes)
Homologues: Orthologues: chimpanzee PER1 (99% identical), macaque PER1 (98% identical), mouse Per1 (92% identical), pig PER1 (92% identical), rat Per1 (92% identical), guinea pig PER1 (91% identical), dog PER1 (89% identical), rabbit PER1 (84% identical), tropical clawed frog per1 (53% identical), zebrafish per1b (52% identical), zebrafish per1a (48% identical), Drosophila melanogaster per (19% identical), and 1 more. Paralogues in human: PER2 (42% identical), PER3 (30% identical).
Diseases named in the same sentence as PER1 in open-access papers:
PER1 is named in the same sentence as 188 diseases in open-access papers, as found by Europe PMC text mining. Sharing a sentence is not in itself a finding about the gene and the disease. The quoted sentences say what the papers report.
breast carcinoma (47 papers, 2010 to 2025). "High expression of PER1 was also found to be associated with metastasis-free survival (MFS) of patients with breast cancer, suggesting an important role of PER1 in the early stages of tumor progression." (PMID 38556856, 2024). "Both Per1 and Per2 can inhibit the occurrence of breast cancer by promoting apoptosis in vivo and reduce the risk of tumorigenesis by indirectly inhibiting c-MYC transcription." (PMID 39012661, 2024). "A significant association was shown between the GG genotype of rs2253820 in PER1 and increased risk of breast cancer (OR = 1.61, 95%CI: 1.00–2.61)." (PMID 36672368, 2023). "Meanwhile, rs2292912 in CRY2, rs2253820 in PER1, rs2289591 in PER1 and rs3027188 in PER1 were positively associated with the risk of breast cancer." (PMID 36672368, 2023). "Our analysis showed that four SNPs, including rs2292912 in CRY2, rs2253820 in PER1, rs2289591 in PER1 and rs3027188 in PER1, were significantly associated with breast cancer risk." (PMID 36672368, 2023). "Previous studies have also reported that aberrant expression and dampened rhythm of PER1 intimately linked to the inception and progression of malignant tumours, such as colon cancer, prostate cancer, breast cancer and non-small cell lung cancer (NSCLC)." (PMID 32429928, 2020). "The women who had one or more protective alleles (derived at least one gene BMAL1 rs2279287 and/or PER1 rs3027178) had a significantly reduced breast cancer risk." (PMID 31739444, 2019). "In recent years, studies have indicated that aberrant PER1 expression was highly linked to the carcinogenesis and development of malignant tumors, such as breast cancer, colon cancer and leukocythemia." (PMID 23405233, 2013). "Furthermore, a meta‐analysis of PER1 expression in human breast cancer survivors indicates that low levels of intratumoral PER1 are associated with poorer prognoses." (PMID 39463009, 2024). "Meanwhile, rs2292912 in CRY2, rs2253820 in PER1, rs2289591 in PER1 and rs3027188 in PER1 could significantly increase the risk of breast cancer." (PMID 36672368, 2023). "Besides, rs2292912 in CRY2, rs2253820 in PER1, rs2289591 in PER1 and rs3027188 in PER1 were positively associated with the risk of breast cancer." (PMID 36672368, 2023). "PER1 is significantly downregulated in various malignant tumor tissues, including breast cancer, lung cancer, prostate cancer, and oral squamous cell carcinoma." (PMID 41451215, 2025). "Ectopic expression of PER1 impairs malignant growth, and reduced levels of endogenous PER1 are found in human breast cancer." (PMID 40046513, 2025). "In breast cancer tissues, high PER1 expression is correlated with longer overall survival and recurrence-free survival (HR: 0.78, 95% CI: 0.63–0.97)." (PMID 41451215, 2025). "Outside of breast cancer, PER1 has similar implications in ovarian cancer, gastric cancer, endometrial cancer, head and neck squamous cell carcinoma, oral squamous cell carcinoma, and non‐small cell lung cancer (NSCLC)." (PMID 39463009, 2024). "Data from human breast cancer patients also demonstrate a positive correlation between PER1 levels and overall survival." (PMID 39463009, 2024). "The tumor inhibitory function of Per1 is evidenced by its ability to significantly impede the proliferation and growth of breast cancer cells, as demonstrated through a distinct diurnal expression pattern." (PMID 39012661, 2024). "Since that time, the molecular underpinnings of the impact of chronobiology on breast cancer progression have been investigated with clock proteins, such as PER1 and PER2, having notable dysregulation in advanced cancers." (PMID 38534802, 2024).
breast carcinoma (continued). "Ectopic PER1 expression in human cancer cell lines impairs malignant growth, and reduced levels of endogenous PER1 is found in human breast cancer." (PMID 35163264, 2022). "Comparing breast cancer to adjacent tissue, PER1, PER2, PER3, and CRY2 levels are decreased; CLOCK is increased; and CRY1 downregulation was found to escalate directly with breast cancer stage." (PMID 35163264, 2022). "The expression levels of rhythm genes, such as CLOCK, PER1, PER2, PER3, CRY2, RORC and TIMELESS, are associated with the metastasis-free survival of breast cancer patients." (PMID 35180863, 2022). "In murine mammary tumor cell lines, Per1 levels revealed a circadian rhythm with a 2.5-fold oscillation amplitude compared to normal tissues." (PMID 34966277, 2021). "The results confirmed that CCND1 was highly expressed in breast cancer tissues and PER1 was low expressed in breast cancer tissues, which is consistent with the results of our data analysis." (PMID 33365308, 2020). "Reduced levels of Per1 and the disruption of the 24 h circadian rhythm were found in liver cancer, breast cancer, colon cancer, lymphoma, and glioma patients." (PMID 31350984, 2019). "Although liquid biopsy remains challenging, a combination of SPAG6, NKX2-6, ITIH5 and PER1 (SNiPER) provides a promising tool for blood-based breast cancer detection." (PMID 31741713, 2019). "The patients having at least one or more risk alleles (among three significant SNPs CRY2 rs10838524; PER1 rs2735611; PER2 rs934945) were significantly associated with an increased breast cancer risk OR = 1.66 (1.17–2.35) p = 0.005." (PMID 31739444, 2019). "Our analysis indicates that five SNPs, BMAL1 rs2279287, CLOCK rs12505266, CRY2 rs10838524, PER1 rs2735611, PER2 rs934945, are significantly associated with the breast cancer risk in the Polish association study." (PMID 31739444, 2019). "Subsequent ROC curve analysis on basis of validation cohort specific CpGs revealed significant results for a combination of SPAG6 and PER1, achieving breast cancer detection with 25% sensitivity." (PMID 31741713, 2019). "The ER-negative (ER-) breast cancer tissue samples had significantly lower PER1 gene expression than the ER-positive breast cancer tissue samples (ER+) (β-coefficient -0.291 p = 0.005)." (PMID 29958276, 2018). "Downregulation of Per1 and Per2 in rodent models initiates higher cancer cell growth, but on the other hand, overexpressed Per2 leads to apoptosis in mouse mammary carcinoma cell lines ETM6." (PMID 29958276, 2018). "rs2253820 in PER1 a synonymous G>A SNP had low level of evidence in breast cancer sub-group, as well as rs7602358 T>G downstream PER2." (PMID 28177907, 2017). "In more than 95 % of breast cancer tissue from 55 women, expression levels of PER1, PER2, and PER3 were severely disrupted in comparison with adjacent non-cancerous tissue." (PMID 27492458, 2016). "Another study illustrated that 95% of the breast cancer cells tested in women showed aberrant promoter methylation in the Period genes, including Per1- and Per2-promoter hypermethylation." (PMID 26220712, 2015). "Dysregulation or loss of PER1 and/or PER2 has been shown in human breast cancer tumor cells when compared with normal cells from adjacent tissue." (PMID 22076133, 2011). "The methylation status of the PER1 promoter is negatively correlated with estrogen receptor (ER)-positive expression in breast cancer, suggesting that PER1 methylation variations may influence ER expression." (PMID 41451215, 2025). "When comparing sporadic and known forms of breast cancer, the expression levels of the PER1 gene are lower, indicating that the hereditary form of the illness may be caused by a possible disruption to the circadian rhythm." (PMID 38892035, 2024). "Breast cancer cells may survive if the promoters of the PER1 and CRY1 genes are methylated since this will prevent these genes from being expressed and will interfere with the circadian rhythm of cells." (PMID 38892035, 2024).
breast carcinoma (continued). "Indeed, attenuation of PER1 expression in murine mammary tumors leads to increased tumor cell proliferation and a shortened survival." (PMID 39463009, 2024). "As to OMIM diseases, PER1 was related to breast cancer and colorectal cancer." (PMID 36385012, 2022). "Additionally, polymorphisms of rhythm genes, including BMAL1, CRY2, PER1, PER2 and PER3, are associated with susceptibility to breast cancer." (PMID 35180863, 2022). "Low PER1 and PER2 expression is linked to breast cancer development and poorer outcomes." (PMID 35163264, 2022). "Employing the previously selected CpGs, PER1 showed a significant higher methylation level in breast cancer patients (mean of 2.58% in benign controls versus 2.87% in breast cancer cases, p = 0.0172) and early invasive breast cancer patients (2.6% versus 2.98%, p = 0.0058)." (PMID 31741713, 2019). "ROC curve analysis revealed that SPAG6 alone detected breast cancer at 50% sensitivity (cut-off 7.1%, 85% specificity), which could be increased to 60% by adding PER1 (cut-off 5.5%, 85% specificity)." (PMID 31741713, 2019). "In addition, genome-wide DNA methylation profiling has shown that PER1 is significantly hypomethylated in ER+/PR+ breast cancer tissues." (PMID 29780357, 2018). "Indeed, down-regulation of PER1 accelerates cell growth in breast cancer, whereas up-regulation of PER1 inhibits cell growth and promotes cell apoptosis in colon, prostate and lung cancers." (PMID 26943040, 2016). "In a study of nurses with breast cancer, exposure to night work was associated with increased methylation of the CLOCK, BMAL1, PER1 and CRY1 genes, compared with controls, suggesting that epigenetic regulation of these clock genes may have a role in breast cancers linked to shift workers." (PMID 33089179, 2019). "They report a similar downregulation of PER1, PER2, CRY2, and HLF, in breast cancer samples while CLOCK, ARNTL(BMAL1), and BHLHE40 levels remained relatively unchanged." (PMID 38319971, 2024). "The expression of six rhythm genes, CRY2, NFIL3, PER1, EGR3, NR1D1 and TIMELESS, was significantly changed in breast cancer compared with normal breast tissues." (PMID 35180863, 2022). "Cancer cells and primary breast cancer tissues were immunostained for the measurement of circadian clock proteins (CLOCK, BMAL1 and PER1) and acetylserotonin methyltransferase (ASMT)." (PMID 33194597, 2020). "The results shown that the expression of TRRERF1, PER1, TUFT1, CCND1, and ENPP2 genes was significantly different in breast cancer and adjacent tissues (p < 0.0001)." (PMID 33365308, 2020). "In the plasma cohort, on basis of SPAG6, PER1 and ITIH5, sensitivity for breast cancer detection was 64%." (PMID 31741713, 2019). "The highest sensitivity for breast cancer detection was however achieved with a combination of SPAG6, PER1 and NKX2-6 (58% sensitivity, cut-off 4.2%, 79% specificity)." (PMID 31741713, 2019). "In the current study, we identified and evaluated SPAG6, PER1 and NKX2-6 as novel epigenetic biomarkers for liquid biopsy-based early breast cancer detection." (PMID 31741713, 2019). "Accordingly, we identified SPAG6, PER1 and NKX2-6 as novel potential biomarkers for minimally invasive breast cancer detection." (PMID 31741713, 2019). "Decreased expression of PER1 and PER2 has also been observed in gliomas, pancreatic cancers and breast cancers." (PMID 33089179, 2019). "Some studies have indicated similar results showing that genes PER1, PER2, PER3, and CRY2 were down-expressed in breast cancer tissues." (PMID 29958276, 2018). "A significantly decreased mRNA level in the breast cancer tissue samples was observed for CRY2 (β-coefficient -0.424, p<0.0001), PER1 (β-coefficient -0.371, p<0.0001), PER2 (β-coefficient -0.149, p = 0.037) and PER3 (β-coefficient -0.231, p = 0.001)." (PMID 29958276, 2018). "Promoter hypermethylation concomitant with a decrease in expression was identified for the circadian genes PER1 and PER2 in breast cancer." (PMID 23033966, 2012).